IL15 (interleukin 15)
Diseases named in the same sentence as IL15 in open-access papers (continued):
Sharing a sentence is not in itself a finding about the gene and the disease.
pancreatic cancer (36 papers, 2017 to 2026). "IL-15 in combination with CD40 agonists showed significant pancreatic cancer suppression, which was also associated with NK cells." (PMID 39309440, 2024). "In a pancreatic cancer (PC) model, aerobic exercise activated the IL-15/IL-15Rα axis to drive CD8+ T cell infiltration, with similar immune responses observed in clinical samples." (PMID 40699773, 2025). "In this study, we explored the activity of NKG2D-CAR T expressing IL-15/IL-15Rα complex (IL15C) on pancreatic cancer." (PMID 40625735, 2025). "We suspect that PSCs secrete IL15 and then activate the receptor on the surface of the pancreatic cancer cell membrane." (PMID 39396119, 2024). "In conclusion, PSCs protect pancreatic cancer cells from ferroptosis by secretion of IL15, which further activates the IL15R-STAT3-GPX4/ACSL3 axis in a paracrine way." (PMID 39396119, 2024). "Colony formation assay demonstrated higher proliferation ability of pancreatic cancer cells after IL15 treatment." (PMID 39396119, 2024). "Our results showed that various inflammatory cytokines, such as IL-1β, IL-6, IL-8, and IL-15, were more expressed in pancreatic cancer than in the matching normal tissue." (PMID 35630552, 2022). "identifies an important role for exercise in driving an immune-mediated anti-tumor effect in pancreatic cancer through the activation of the IL-15/IL-15Rα axis." (PMID 36225922, 2022). "Harnessing of MSCs in gene therapy of pancreatic cancer has been investigated by inserting several genes such as IL15, IFN- β, miRNAs (miR-126 and miR-1231), TRAIL, HSV-TK, and NK4 into MSCs to release encoded products directly or indirectly with exosomes." (PMID 34249257, 2021). "The data of this study showed that secreted IL-15/IL-15Rα complex could enhance the cytotoxic effect of NKG2D-CAR T cells on pancreatic cancer cell lines and could also promote the proliferation and survival of T cells, especially CD8+ T cells." (PMID 40625735, 2025). "Therefore, we suspect that IL15 can be used as a cancer-promoting factor to promote the growth of pancreatic cancer cells." (PMID 39396119, 2024). "On the one hand, the IL-15 secreted by pancreatic stellate cells protects pancreatic cancer cells by improving ferroptosis resistance; on the other hand, the IL-15 secreted by pancreatic stellate cells can also activate T cells and NK cells to play an antitumor immune role." (PMID 39396119, 2024). "Therefore, we added IL15 to pancreatic cancer cell culture medium, and the results confirmed that IL15 can promote the proliferation and ferroptosis resistance of pancreatic cancer cells." (PMID 39396119, 2024). "IL-10 modified hMSCs could inhibit the growth of pancreatic cancer, and IL-15 produced by MSCs could also significantly inhibit the growth of pancreatic cancer." (PMID 35281017, 2022). "Furthermore, we used small interfering RNA to silenceIL15 in activated PSCs and detected whether it affects the protein level of pancreatic cancer cells.IL15 silencing decreased IL15RA, p-STAT3, GPX4 and ACSL3 expression levels." (PMID 39396119, 2024). "Therefore, whether IL-15 secreted by pancreatic stellate cellsin vivo can protect pancreatic cancer cells remains to be verified by further animal experiments." (PMID 39396119, 2024). "Previous studies have shown that IL15 may be used for immunotherapy in pancreatic cancer." (PMID 39396119, 2024). "It was determined that Anti-MICB-CAR-NK cells co-treated with pancreatic cancer tumor cell line PANC-1 for 24 h secreted significant quantities of Anti-MICB-scFv and IL-15." (PMID 41516373, 2026). "Our results revealed that activated PSCs secrete IL15, which upregulates the expression of IL15RA in pancreatic cancer cells via a paracrine signaling pathway." (PMID 39396119, 2024). "Of the five most used proteins in the BTC signatures (IL-6, IL-15, PTN, CCL23, and MUC-16), only IL-6 was used in the primary pancreatic cancer signatures." (PMID 36831406, 2023).
pancreatic cancer (continued). "Freshly harvested tumor tissues (colorectal and pancreatic cancer) were procured for TIL expansion using IL-2, IL-15 and IL-21." (PMID 30400835, 2018). "For example, after the influence of IL-15 and TGF-β, NK transforms into ieILC1s, which inhibits cancer, and ILC1s (which has weak cytotoxicity) or anoxic environment mediates ILC2s into ILCreg phenotype, which promotes pancreatic cancer." (PMID 39309440, 2024). "IL-15-engineered UCMSCs can specifically home to pancreatic cancer sites, and a sufficient amount of UCMSC-IL15 has been observed to survive to release IL-15, which could significantly suppress the growth of pancreatic cancer." (PMID 36834969, 2023).
diabetes (34 papers, 2012 to 2025). "This shows higher NK cell SPON2 expression occurs in a TGFβ “rich” NK cell suppressive microenvironment and diabetes is associated with higher PBMC IL15 and TGFβ expression in CAD patients." (PMID 39941136, 2025). "IL-15 deficiency, due to mutations in its gene, has been extensively studied in many diseases, such as liver injury, diabetes and allergy." (PMID 36467072, 2022). "More recently the pro-inflammatory cytokines interleukin-15 (IL-15), interleukin-18 (IL-18) and interleukin-8 (IL-8) have been found to be more specific risk factors for coronary artery disease, diabetes and some cancers." (PMID 31011016, 2017). "In addition, diabetes can impair the mTOR pathway, causing a reduction in IL-15 activation, leading to a reduction in IGF-1 and wound closure." (PMID 33291435, 2020). "TGF-β, IL-1Ra and IL-15 levels drop abruptly while α-Defensin-1 peaks during pre-diabetes to diabetes transition." (PMID 38327565, 2024). "Higher levels of IL-15 have been reported in pulmonary TB and diabetes mellitus, reflecting their inflammatory characteristics." (PMID 35153741, 2021). "Another mechanism of epidermal γδ T cell dysfunction in obesity and diabetes is the disruption of the IL-15-IGF-1 loop." (PMID 33291435, 2020). "Conversely, some studies have shown that IL-15 treatment reduces the development of diabetes in NOD mice, probably via a stimulatory effect of IL-15 on NK cells, suggesting a protective role for this cytokine in type 1 diabetes." (PMID 31772933, 2019). "The potential role of IL-15 and IL-6 in the pathogenesis of diabetes is still discursive, and only a handful of reports concerning their role in LADA are available." (PMID 31772933, 2019). "A statistically significant difference between controls and subjects with diabetes at baseline was observed in aqueous humor levels of the following cytokines: IL-10, IL-12p70, IL-12p40, IL-15, EGF, FGF-2, VEGF, MIP-1β, MCP-3 and MDC (p < 0.05; p < 0.001)." (PMID 30410092, 2018). "Furthermore, these macrophages exhibited higher IL-15 and IL-18 expressions in individuals with diabetes and NASH (1.7-fold and 2-fold, both p < 0.05, respectively)." (PMID 40362271, 2025). "A similar positive association has been previously reported between systemic inflammation, i.e., increased serum cytokine IL-1 β, IL-3, INF- γ, and GADA levels in patients with both types of diabetes and significantly higher IL-6 and IL-15 concentrations in autoimmune diabetes." (PMID 37025699, 2023). "In addition, pancreatic β cells overexpress IL-15 and Il-5α double transgenic mice, which appear similar to human insulin antibodies, which induce β cell destruction, while inhibiting IL-15 and IL-5α that can reverse the progression of diabetes." (PMID 35242879, 2022). "One study conducted on NOD mice showed that IL-15 reduces the cumulative incidence of diabetes, suggesting that this reduction could be due to a down-regulation of beta-cell apoptosis." (PMID 31772933, 2019). "Therefore, impaired epidermal IL-15 production was an important reason to result in dysfunctional DETCs in diabetes." (PMID 29225596, 2017). "This implies that, in diabetes setting, impaired mTOR pathway and weakened productions of IL-15 and IGF-1, exhibit mutual effects and may reach a low-level equilibrium state, an important mechanism that causes dysfunction of DETC and defective wound repair." (PMID 29225596, 2017). "Furthermore, IL-15 and IGF-1 in the epidermis were regulated by rapamycin and STZ under similar kinetics, which provides additional support for the coordinated suppression of IGF-1 and IL-15 in diabetes." (PMID 28729536, 2017). "To determine whether a similar pathway of mTOR and IL-15 suppression may explain the reduced DETC homeostasis in the STZ diabetes model, we examined the effects of diabetes induction over a timecourse of STZ treatment." (PMID 28729536, 2017). "Significant main effect of diabetes was found in IL15 (P = 0.001)." (PMID 27512375, 2016).
diabetes (continued). "To understand the mechanism underlying the effects of ASCs on CAIA, we examined the serum levels of five cytokines (IL-15, IL-1α, IL-6, IL-7, and TNFα), five diabetes-related hormones (resistin, GIP, GLP-1, ghrelin, and leptin), and adiponectin using multiplex immunoassays." (PMID 26210906, 2015). "Further research is needed in order to determine whether these properties are generalizable to retinal tissue, but it is possible that the decrease in IL-15 signaling reflects the impaired glucose and insulin responses that ultimately precipitate diabetes complications such as retinopathy." (PMID 34861815, 2021). "Blocking interferons on their own does not prevent diabetes in knockout NOD mice, so we tested whether JAK inhibitor action on signaling downstream of common γ chain cytokines, including IL-2, IL-7 IL-15, and IL-21, may also affect the progression of diabetes in NOD mice." (PMID 33343569, 2020). "It has also been observed that diabetes-prone BioBreeding (BBdp) rats housed in specific germ-free (GF) conditions and weaned onto cereal diets displayed an upregulation of the interferon gamma (Ifng) and interleukin 15 (Il15) genes and a downregulation of the forkhead box P3 (Foxp3) gene." (PMID 25421534, 2014). "Two cytokine families that are important in diabetes pathogenesis are interferons (IFN), including type 1 IFNs and IFN-γ, and the common γ chain cytokines, including IL-2, IL-4, IL-7, IL-9, IL-15, and IL-21." (PMID 33343569, 2020). "To better understand the potential role of these myokines in T2D, we tested the hypotheses that IL-15 and irisin serum concentrations correlate with cardiometabolic risk parameters and are different in subgroups of T2D patients with or without diabetes complications independently of ethnicity." (PMID 31506722, 2020). "In addition, we could reproducibly show for the German and Korean cohort that irisin and IL-15 serum concentrations are not related to cardiometabolic risk factors or the presence of diabetes complications." (PMID 31506722, 2020). "Our results verify that diabetes induction disrupts DETC homeostasis, which can be observed at the site of scarring and in intact epidermis and can be improved by administration of IL-15 after STZ treatment." (PMID 28729536, 2017). "Our data suggest that in the setting of diabetes, reduced IGF-1, impaired mTOR pathway activation and reduced IL-15 in the epidermis function coordinately to promote altered DETC homeostasis and delayed skin wound closure." (PMID 28729536, 2017). "To further understand the process of homeostasis of DETCs, including the coordinated roles of IGF, mTOR and IL-15, we examined homeostasis in the STZ mouse model of diabetes." (PMID 28729536, 2017). "The extreme decrease of IL-15 in CHB patients with T2DM might be due to the synergistic effects of chronic HBV infection and diabetes." (PMID 35801423, 2023). "In this study, we demonstrate that acute melioidosis patients rely on NK cells for survival and excessive levels of pro‐inflammatory cytokines IL‐15 and biologically inactive IL‐18 contribute to poor outcome independent of diabetes comorbidity." (PMID 31032897, 2019). "Suppression of IL-15 and suppressed phosphorylation of several components of the mTOR pathway, including S6K and AKT, occur upon treatment of mice with STZ, which further supports their coordinate role in diabetes." (PMID 28729536, 2017). "Further studies are essential to firmly establish the unknown factors involved in the IL-15-Jak3/STAT3 signaling axis for the potential treatment and/or prevention of metabolic disorders, such as insulin resistance or diabetes." (PMID 28066259, 2016). "In the epidermis, IL-15, IGF-1, and mTOR are known to regulate the maintenance of DETCs; however, it is unclear how these molecules may intersect to regulate DETC homeostasis in diabetes." (PMID 28729536, 2017).
diabetes (continued). "Salivary IL-15 and MCP1 were 1.3-fold higher in dogs with Diabetes mellitus compared to controls (P < 0.05 and P < 0.01, respectively), while KC-like chemokine was 1.4-fold lower in dogs with DM as compared with controls (P < 0.01)." (PMID 38521919, 2024). "Thus, IGF-1, mTOR and IL-15 all are suggested to regulate homeostasis of DETCs, but the coordinate regulation of these pathways of DETC homeostasis in diabetes is not well characterized." (PMID 28729536, 2017).
lymphopenia (33 papers, 2007 to 2025). Reduction in the number of lymphocytes. "Genetic ablation of IL-15 caused lymphopenia due to substantially reduced numbers of TMEM, NK cells, NKT cells, and IEL in the skin and gut." (PMID 38405398, 2024). "Employing the protocol often results in lymphopenia that is associated with elevated serum levels of the homeostatic cytokines IL-7 and IL-15, which expands the autoreactive CD8+ T-cell population." (PMID 22013505, 2011). "This global increase could be driven by lymphopenia-associated IL-15 signaling, as IL-15 is known to promote CPT1a expression and FAO engagement and promote mitochondrial biogenesis." (PMID 33013907, 2020). "Collectively, these data suggest a mechanism of prolonged, lymphopenia-driven increase of systemic IL-7 and IL-15 concentrations after acute SARS-CoV-2 infection, which sustains increased IL-2R and decreased IL-7R expression." (PMID 41310351, 2025). "IL-15 promotes cell survival during development or in lymphopenia through JAK/STAT and PI3K/AKT pathway-mediated regulation of both anti- and pro-apoptotic factors of the Bcl-2 protein family." (PMID 38405398, 2024). "T effector cells also showed a reduction in pro-apoptotic proteins Bcl-Xs and Bax in response to IL-15 in a lymphopenia mouse model." (PMID 38405398, 2024). "Accordingly, “virtual memory” T cells are generated in peripheral tissues by IL-15 signaling, whereas “homeostatic memory” T cells are produced via lymphopenia-induced proliferation in peripheral organs in an IL-7- and IL-15-dependent manner." (PMID 37887277, 2023). "Homeostatic proliferation (HP) is a physiological process that reconstitutes the T cell pool after lymphopenia involving Interleukin-7 and 15 (IL-7 and IL-15), which are the key cytokines regulating the process." (PMID 33809452, 2021). "Nevertheless, for example, IL-7- and IL-15-driven T cell proliferation induced by lymphopenia can promote the numerical recovery of T cells." (PMID 34305933, 2021). "Instead, repopulation of the peripheral T cell population is predominantly driven by lymphopenia-induced proliferation, mediated by the increased availability of γc cytokines, such as IL-7 and IL-15." (PMID 33013907, 2020). "Antigen-independent induction of CD8+ T-cell proliferation in co-cultures with IL-15-producing dendritic cells presenting self-peptides in murine models of lymphopenia has been demonstrated." (PMID 31027182, 2019). "We demonstrated that transferred Te cells exhibited prolonged survival and enhanced memory formation during lymphopenia, and that IL-15 signaling is central to the observed properties of transferred T-cells." (PMID 27158441, 2016). "We next assessed the stimulatory effect of IL-7 and IL-15 on Te cells, thus mimicking the situation of our study of the in vivo effect of IL-15 signaling on transferred Te cells in lymphopenia." (PMID 27158441, 2016). "In vivo transferred T-cells up-regulate expression of Bcl-2, FoxO1, Eomes and Atg7, enhance the phosphorylation of pSTAT5 and ULK1 and activate the mitochondrial biogenesis via IL-15 signaling in lymphopenia." (PMID 27158441, 2016). "This would provide a plausible mechanistic explanation for a dominant role for IL-15 in prolonged T-cell survival and enhanced Tm cell formation of transferred Te cells in lymphopenia." (PMID 27158441, 2016). "The first is called homeostatic memory or virtual memory that arises both in the lymphopenia and physiological environment in the periphery, in an IL-15-dependent manner." (PMID 27766099, 2016). "The induction of lymphopenia is well known to enhance lymphocyte responses to homeostatic cytokines, such as IL-15 and IL-7; however, the mechanism responsible for enhanced IL-15 responses has been unclear." (PMID 25756182, 2015). "As anticipated, this period of relative CD4 lymphopenia was accompanied by an elevation in IL-7 and IL-15 plasma levels (compared to baseline pre-infusion levels)." (PMID 19270751, 2009).
lymphopenia (continued). "In addition to survival, antigen-independent homeostatic proliferation induced during lymphopenia restores the lymphocyte pool through homeostatic cytokines such as IL-15." (PMID 38405398, 2024). "Various cell types produce IL-7 and IL-15, primarily in lymphoid tissues under lymphopenia." (PMID 33809452, 2021). "Second, lymphopenia triggers immune system regeneration phase, marked by lymphocyte proliferation homeostasis motored by interleukin (IL)-7 and IL-15, so the immune response could return to normal state in a period after chemotherapy." (PMID 34837913, 2021). "It is well-known that irradiation removes the sinks for homeostasis cytokines such as IL-7 and IL-15 leading to IL-7 and IL-15 increase in lymphopenia, and induces radiation-sensitive hematopoietic cell apoptosis, leading to releasing its IL-15Rα and subsequent formation of IL-15/IL-15Rα complexes." (PMID 27158441, 2016). "Here, we transferred in vitro-activated transgenic OT-I CD8+ effector T-cells into irradiation (600 rads)-induced lymphopenic C57BL/6, IL-7 knockout (KO) and IL-15 KO mice, and investigated the survival and memory formation of transferred T-cells in lymphopenia." (PMID 27158441, 2016). "Furthermore, homeostatic cytokines such as IL-7 and IL-15, that are prevalent during lymphopenia, have been shown to be able to substitute for IL-2 signaling in activated effector cells." (PMID 22383993, 2012). "Because it is generally assumed that during lymphopenia the availability of growth and survival factors increases, which has in particular been shown for IL-7 plasma levels, we also determined plasma levels of IL-7 and IL-15 between 12 and 24 months post-autoHSCT." (PMID 33538246, 2021). "Lymphopenia-induced proliferation of naïve CD8 T cells is driven by signals through both the TCR (engaging self peptide/MHC ligands) and the cytokines IL-7 and IL-15." (PMID 22879925, 2012). "The levels of plasma IL-15 were modestly increased and increased mortality in patients with severe lymphopenia compared to patients without lymphopenia." (PMID 38114466, 2023). "As opposed to NKT cells, IL-15 promoted TMEM by inhibiting T-bet and promoting Eomes upregulation and memory T cell metabolism through the ULK1/Atg7 autophagy pathway in mouse models of lymphopenia." (PMID 38405398, 2024).